MTOR (mechanistic target of rapamycin kinase)
Diseases named in the same sentence as MTOR in open-access papers (continued):
Sharing a sentence is not in itself a finding about the gene and the disease.
tumor (continued). "Despite the lack of statistical robustness, the identified survival pattern corroborates the concept that the activation of the PI3K/Akt/mTOR pathway may enhance a more advantageous tumour phenotype in certain patients." (PMID 41465766, 2025). "Some research indicates that the HER2 signaling pathway may indirectly regulate PD-L1 expression, possibly through activation of the PI3K/AKT/mTOR pathway or by promoting the secretion of immunosuppressive cytokines in the tumor microenvironment." (PMID 40519936, 2025). "Consequently, mTOR inhibitors such as rapamycin (sirolimus) can effectively reduce glycolysis, immunosuppressive activity, and the percentage of tumor‐infiltrating M‐MDSCs in tumor‐bearing mice." (PMID 40452814, 2025). "PI3K/Akt/mTOR was observed to be crucial for the growth and multiplication of tumor cells." (PMID 40176859, 2025). "BA treatment slightly increased Bax and Caspase-3 levels while decreasing Bcl-2 expression, consistent with studies showing that betulinic acid suppresses tumor growth through activation of mTOR-regulated apoptotic signaling and modulation of the Bax/Bcl-2/caspase axis." (PMID 41470183, 2025). "In addition, mTOR signaling can further promote the rapid division of tumor cells and the malignant progression of tumors by activating genes related to protein synthesis and cell growth." (PMID 40149733, 2025). "Suppression of tumor growth, angiogenesis, induction apoptosis, regulation Akt/mTOR." (PMID 40612872, 2025). "Furthermore, in comparison to the EVs group and TMTP1-EVs group, the mice in the TSRP + DIR group, TSRP-EVs group, and TMTP1-TSRP-EVs group exhibited significantly decreased phosphorylation levels of PI3K, Akt, and mTOR in tumor tissues near the bone." (PMID 40328748, 2025). "Dysregulated mTOR signaling promotes tumor cell proliferation and survival." (PMID 40547482, 2025). "This fusion likely serves as the driver mutation for the neoplasm through activation of the mTOR pathway given the lack of other identifiable driver mutations on molecular testing." (PMID 40091373, 2025). "Of note, the PI3K/AKT/mTOR axis is frequently hyperactivated in TNBC to regulate tumor proliferation and survival, yet existing mTOR inhibitors show limited efficacy in this subtype due to feedback activation of compensatory pathways and off - target effects that reduce their specificity for TNBC." (PMID 40949144, 2025). "Furthermore, mTOR inhibition with well-known pharmacological agents revealed that mTOR activation is required for YAP-mediated tumor progression." (PMID 39779672, 2025). "Also, PI3K/AKT/mTOR can regulate the expression of PD‐L1 on tumor cells, suppressing T cell‐mediated cytotoxicity." (PMID 40182139, 2025). "The culture conditions without glucose reduced the ability of teHDNs to store obtained lipids in LDs; decreased their proliferation, DGAT1 expression, and mTOR phosphorylation levels; and decreased their survival ability and ability to promote tumor cell proliferation." (PMID 41214328, 2025). "Potentially, targeting NR2F1 and mTOR in both compartments, i.e., the tumor and TME, may amplify the therapeutic effect of future targeted inhibitors." (PMID 40955667, 2025). "Moreover, CXCL3 derived from both tumor cells and stromal cells was shown to promote the malignant behaviour of tumor cells through activation of the PI3K/AKT/mTOR signalling pathway." (PMID 41259383, 2025). "Notably, increased mTOR signaling has been associated with poor prognosis and resistance to therapy in OSCC, making it a significant marker for aggressive tumor behavior and a viable target for therapeutic intervention." (PMID 39781358, 2025). "However, in tumors such as lung cancer, miR-126 can inhibit tumor angiogenesis by lowering VEGFA levels and activating signaling pathways such as Akt/mTOR/Erk1/2, ultimately suppressing tumor growth." (PMID 40332376, 2025).
tumor (continued). "In the early stages of tumors, it may exert protective effects by maintaining cell differentiation, inhibiting invasion and metastasis, and modulating signaling pathways (e.g., PI3K/AKT/mTOR), thereby restricting tumor malignancy progression." (PMID 41153357, 2025). "Notably, in EGFR-mutant LUAD, GREM1 overexpression perpetuates PI3K/AKT/mTOR pathway activation, sustaining tumor cell survival and proliferation, which consequently attenuates the efficacy of EGFR-TKIs such as osimertinib." (PMID 41048340, 2025). "By inhibiting both EGFR and PI3K/mTOR pathways, this approach may reduce tumor cell viability more effectively and delay the development of resistance." (PMID 40650170, 2025). "Hyperactivation of the PI3K/Akt/mTOR pathway in tumor cells likewise confers immune resistance." (PMID 41374963, 2025). "However, mTOR is often overexpressed in tumor cells, leading to vigorous glycolytic metabolism that promotes tumor growth, metastasis and invasion of healthy tissues." (PMID 39648951, 2025). "However, acquired chemoresistance presents a major challenge in oncology, as changes in key regulatory pathways, such as PI3K/AKT/mTOR, contribute to tumor resistance to conventional therapies." (PMID 40278356, 2025). "Additionally, given the important role of the mTOR pathway in lactate metabolism, combination therapy with mTOR inhibitors and lactate metabolism or transport inhibitors is considered to enhance anti-tumor immunity." (PMID 40045411, 2025). "Furthermore, exosomal CMTM6 activates the mTOR signaling pathway in tumor-associated macrophages, enhancing CCL2 secretion, which further promotes M2a polarization and accelerates tumor metastasis." (PMID 40761779, 2025). "EdU staining and CCK8 analysis revealed that in NR6A1-siRNA-treated cells, the addition of MHY1485 restored the proliferative phenotype of A549 cells to a certain extent, suggesting that NR6A1 promotes tumor cell glycolysis and proliferation via mTOR signaling." (PMID 41219936, 2025). "BCAAs support the growth and proliferation of tumor cells by promoting the mTOR signaling pathway." (PMID 40438606, 2025). "This further suggests that PI3K pathway alterations are a frequent molecular event in TNBC and that the respective contributions of RICTOR, PIK3CA, and PTEN to mTOR hyperactivation may drive tumor progression." (PMID 40019775, 2025). "The oxidative stress triggered by AF may sensitize tumor cells to mTOR inhibition, enhancing the antiproliferative effects of sirolimus." (PMID 41304874, 2025). "Notably, nine of these drugs belonged to the class of PI3K/MTOR inhibitors, which exert anti-tumor effects by targeting the PI3K/MTOR signaling pathway." (PMID 40777132, 2025). "For instance, lncRNAs may enhance tumor resistance via autophagy mediated by the ERK/mTOR, AKT/mTOR, or TGF-β/Smad3 pathways." (PMID 40223929, 2025). "mTOR activation enhances cellular proliferation and promotes tumour progression." (PMID 40806771, 2025). "Mechanistic studies suggest that FASN may modulate the AMPK/mTOR and Wnt signaling pathways, contributing to tumour progression, cell proliferation, invasion, and metastasis." (PMID 41154605, 2025). "Dysregulation of these receptors and their downstream signaling pathways, including PI3K/AKT/mTOR, Ras/Raf/MAPK, and phospholipase C (PLCγ), has been implicated in tumor progression and it is associated with poor prognosis, although the mechanism by which this happens is still unclear." (PMID 41465387, 2025). "Moreover, the PI3K/Akt/mTOR signaling pathway serves as a critical regulatory axis in tumor development." (PMID 39991629, 2025). "Notably, PD-L1 expressed on tumor cells directly enhances tumor glycolysis by activating the PI3K/AKT/mTOR pathway, creating a metabolic advantage for tumor survival and further suppressing T cell activity." (PMID 41281744, 2025).
tumor (continued). "To further clarify the association between mTOR signaling pathway activity and bone metastasis, we revealed that tumor tissues from PCa patients with bone metastasis exhibited significantly elevated mTOR signaling pathway activity compared to localized-stage PCa using the GSE32269 dataset." (PMID 41050665, 2025). "Meanwhile, mTOR induction in a TLR4-dependent manner by bacterial PAMPs may increase macrophage cytotoxicity against tumor cells." (PMID 40806725, 2025). "Tumor cells inhibit the PI3K/Akt/mTOR pathway in T cells, impairing their function." (PMID 40563651, 2025). "mTOR activation leads to more vascularised tumours by activating HIF-1α-induced VEGF signalling." (PMID 40806771, 2025). "Furthermore, ART exhibited strong interactions with AKT1, a key molecule in the PI3K/AKT/mTOR signaling pathway, which was widely activated in various malignancies and promotes tumor cell survival and invasive behaviors." (PMID 40303931, 2025). "Under normal conditions, mTOR is important for tumor propagation and progression." (PMID 40621878, 2025). "Additionally, the PI3K/AKT/mTOR pathway enhances tumor cell proliferation, invasion, metastasis, and angiogenesis while inhibiting apoptosis and increasing resistance to treatment." (PMID 39873475, 2025). "For example, curcumin can directly inhibit mTOR activity, a core factor in regulating cellular growth and metabolism, reduce protein synthesis in tumor cells, and simultaneously activate autophagy and the ubiquitin-proteasome system to enhance protein degradation." (PMID 41515171, 2025). "As these genes are involved in oxidative stress responses, RAS signaling, and mTOR regulation, this suggests that the CC genotype in TNBC may be associated with a more proliferative and signal-enriched tumor phenotype in postmenopausal BC samples." (PMID 40565184, 2025). "Nitazoxanide, a thiazolide, exerts anti-tumor effects by activating AMPK while inhibiting AKT/mTOR and Wnt/β-catenin signaling, thereby reducing proliferation and stemness—effects that are further enhanced when combined with farnesoid X receptor (FXR) agonists." (PMID 41439989, 2025). "This highlights the importance of PI3K/MTOR-related targets in tumor therapy." (PMID 40777132, 2025). "mTOR inhibitors have been shown to be immunosuppressants with anti-tumor activity." (PMID 40061426, 2025). "Activated Akt exerts its effects by stimulating the downstream mTOR pathway or by inhibiting proteins such as Bad and Caspase-9, which regulate cell proliferation, differentiation, apoptosis, and migration, contributing to radiation resistance in tumor cells." (PMID 41178971, 2025). "This bidirectional interaction between ECM-integrin signalling and mTOR-MMP axis may underlie the coordinated activation of these pathways in CRC and highlights their mechanistic relevance in tumour progression." (PMID 40860666, 2025). "Inhibition of the mTOR pathway may influence anti‐tumor immunity, malignant progression, and tumor response." (PMID 41322031, 2025). "Additionally, mTOR boosts the capacity of tumor cells to invade and metastasize through its control over the restructuring of the cellular cytoskeleton and the production of matrix metalloproteinases." (PMID 41142018, 2025). "Meanwhile, ICMT inhibitors impede mTOR-mediated autophagy, disrupt tumor cell cycle progression, and augment anticancer activity.UCM- 1336 is a new generation of ICMT inhibitors, a promising drug candidate with more potent enzyme inhibition and lower toxicity than cysmethynil." (PMID 40335986, 2025). "Inhibitors of mTOR were developed as inhibitors of tumor cell proliferation and survival." (PMID 40821795, 2025). "In addition, MALAT1 promotes cell growth and tumor metastasis by controlling TCF7L2 expression via mTOR-mediated TCF7L2 translation, thereby facilitating aerobic glycolysis and repressing gluconeogenesis in HCC." (PMID 41361062, 2025).
tumor (continued). "Apigenin inhibits AKT/mTOR signaling, which triggers the autophagy–lysosomal degradation of β-catenin in Wnt-activated and colorectal cancer cells, ultimately dampening Wnt signaling and limiting tumor cell growth." (PMID 41155376, 2025). "PTEN has been found to interfere with tumor progression by inhibiting the PI3K/Akt/mTOR pathway." (PMID 39890782, 2025). "Secalonic acid D suppresses tumor cell survival by targeting the Akt/mTOR/p70S6K pathway, which, in turn, affects key proangiogenesis factors, such as the hypoxia-inducible factor 1α, vascular endothelial growth factor receptors, and the matrix metalloproteinase MMP-2/MMP-9." (PMID 40429170, 2025). "Moreover, the tumor’s consumption of glucose can limit its availability to T cells, reducing mTOR signaling, IFNγ production, and the glycolytic capacity of T cells, further dampening their anti-tumor activity." (PMID 41019045, 2025). "Moreover, aberrant mTOR signaling has been observed in various tumors, where its activation promotes tumor growth and metastasis." (PMID 40775338, 2025). "The PI3K/AKT/mTOR signaling pathway is a major driver of tumor metabolism, growth, and survival." (PMID 40227587, 2025). "In addition, a more than 2-fold reduction in p-mTOR expression was shawn in the SLC25A20 knockdown tumor tissues." (PMID 40521210, 2025). "Given that the FLCN mutation, a tumor suppressor of the mTOR pathway, is central to the pathogenesis of BHDS, inhibiting this pathway could potentially decrease the risk of tumor recurrence after transplantation." (PMID 40740168, 2025). "While the PI3K/AKT/mTOR pathway can enhance T cell and NK cell function, excessive activation leads to immune cell exhaustion and suppression, ultimately impairing an effective anti-tumor response." (PMID 40486875, 2025). "The other subunit of the mTOR complex, mTORC2, also contributes to tumor development." (PMID 40647529, 2025). "Finally, rtSPIRE1 stabilizes LRP5 by inhibiting its ubiquitination, activating the PI3K/AKT/mTOR signaling pathway to promote tumor progression." (PMID 40713830, 2025). "In tumors, loss-of-function mutations in the tumor suppressor gene PTEN impair its negative regulatory effects on PI3K signaling, leading to decreased PI3K degradation and sustained phosphorylation-driven activation of Akt and mTOR." (PMID 40443737, 2025). "Indeed, mTOR has been shown as an intrinsic regulator of the differentiation and immunosuppressive function of M-MDSCs in alloskin-grafted and tumor-bearing mice models." (PMID 40725182, 2025). "Additionally, rapamycin, a specific mTOR inhibitor, shows a promising tumor inhibitory effect combining with ferroptosis inducers in vitro and in vivo." (PMID 41049011, 2025). "Autophagy has been shown to support tumor survival in GEP-NENs under mTOR inhibition." (PMID 40647381, 2025). "The favourable‐prognosis subgroup (Pattern 1) demonstrated significant enrichment of established oncogenic pathways, including MAPK and mTOR signalling cascades, consistent with the emerging paradigm of RiboSis‐mediated metabolic reprogramming in tumour progression." (PMID 41284374, 2025). "However, the expression of mTOR was reduced while PTEN increased when SRSF1 was downregulated in tumor cells." (PMID 39837814, 2025). "Prenatal therapy with mTOR inhibitors, therefore, appears to improve fetal cardiac function by reducing tumor burden and may contribute to better perinatal outcomes, although validation in future studies is required." (PMID 41438139, 2025).
tumor (continued). "Targeting mTOR and TF remodels the tumor microenvironment by reducing fibrin deposition (ameliorating hypercoagulability), altering collagen distribution (attenuating stromal fibrosis), decreasing CD31+, α-SMA+ vessel density, and diminishing CD206+, F4/80+ immunosuppressive M2 TAM infiltration." (PMID 40896442, 2025). "In contrast, several tumor-promoting pathways, such as the mTOR signaling pathway, PI3K-Akt signaling pathway, EGFR tyrosine kinase inhibitor resistance, TGF-β signaling pathway, and Ras signaling pathway, were significantly downregulated following the ER-Cy-poNO2-mediated phototherapy." (PMID 40283929, 2025). "Similarly, the dual treatment of docetaxel and mTOR inhibitor temsirolimus results in a remarkable reduction of tumor growth in prostate and breast cancer animal models." (PMID 39811803, 2025). "The mTOR pathway, a central regulator of cell growth and metabolism, plays a crucial role in brain development, where its hyperactivation leads to abnormal neuroplasticity, tumor formation, and heightened neuronal excitability." (PMID 40358185, 2025). "Thus, PTEN is proposed to act as a tumor suppressor by regulating the PI3K–Akt–mTOR signaling network." (PMID 40430079, 2025). "In summary, the overexpression of FOXK2 can enhance FAO metabolism in tumor cells through mechanisms that can be outlined as follows: it increases the binding affinity of FOXK2 to the mTOR, upregulates the expression of DRP1, and promotes FAO, thereby driving tumor progression." (PMID 40641601, 2025). "Furthermore, Kyoto Encyclopedia of Genomes (KEGG) pathway enrichment analysis demonstrated significant enrichment of DEGs in tumor‐associated signaling pathways including PI3K/AKT pathway and mTOR pathway." (PMID 39836493, 2025). "Dactolisib, a PI3K/mTOR inhibitor, significantly suppressed tumor cell proliferation." (PMID 40463372, 2025). "Additionally, high TYMS levels can activate the mTOR signaling pathway, further promoting tumor proliferation." (PMID 40496862, 2025). "Furthermore, sustained activation of the PI3K/AKT/mTOR pathway not only facilitates rapid tumor cell division but also regulates glycolytic enzymes, allowing tumor cells to adapt to high metabolic demands." (PMID 41267926, 2025). "Upon HPV infection, mTOR activation supports viral replication and tumor growth." (PMID 40667502, 2025). "KIF3C may inhibit tumor growth by activating the PI3K/AKT/mTOR signaling pathway, thereby prolonging the survival time of patients." (PMID 40964093, 2025). "Postnatal supplementation with mTOR inhibitors may still be necessary, as seen in some cases where continuous therapy was required to maintain tumour reduction or prevent postnatal disease progression." (PMID 39518472, 2024). "In the present work, we explored whether the gene expression of Beclin1 and mTOR as autophagy markers shows any difference between normal and tumour samples." (PMID 38164366, 2024). "In CRC, LOI of IGF2 can enhance cell autophagy through the PI3K/Akt/mTOR pathway, whereas it might promote tumor formation through the IGF2-INSR pathway in SFT." (PMID 38812777, 2024). "Additionally, the production of a large amount of lactate is believed to enhance tumor radioresistance through the GPR81/mTOR/HIF-1/STAT3 pathway." (PMID 38993643, 2024). "Phosphorylation of mTOR is considered a marker of tumour progression and mediates the activation of downstream targets such as S6K and 4E-BP1, the activation of which leads to an increased risk of tumor development and poor prognosis." (PMID 39898323, 2024). "In summary, the absence of intra‐tumoral TLS abundance is associated with mTOR signaling activation and uncontrolled cell cycle progression in tumor cells, indicating unfavorable prognosis in HCC‐LT." (PMID 38498682, 2024). "In the tuberous sclerosis complex, which is inherited in 50% of cases, foetal tumours may develop because of activation of the mTOR pathway." (PMID 39579091, 2024).